TNF (tumor necrosis factor)
Diseases named in the same sentence as TNF in open-access papers (continued):
Sharing a sentence is not in itself a finding about the gene and the disease.
psoriasis (continued). "In patients with psoriasis, the inflammatory environment characterized by elevated levels of pro-inflammatory cytokines, including TNF-α and IL-17, may further enhance VEGF expression, thereby promoting angiogenesis and the development of cherry angiomas." (PMID 40282856, 2025). "Research has shown that the use of biologic therapies, particularly TNF-α inhibitors, offers benefits beyond cutaneous control in patients with psoriasis, including a significant reduction in the incidence of cardiovascular events, such as acute myocardial infarction." (PMID 40698258, 2025). "The study, “Serum Levels of Tumor Necrosis Factor—Alpha in Patients with Psoriasis” by Ocvina-Kurtovic, Nermina, and Emina Kasumagic-Halilovic, reported that elevated serum levels of TNF-α were observed in psoriasis patients, demonstrating a strong correlation with disease severity." (PMID 40310305, 2025). "However, there is evidence that specific biological therapies used in psoriasis, particularly those based on tumor necrosis factor (TNF) inhibitors, can reactivate latent infection with Mtb." (PMID 40310305, 2025). "The pathogenesis of psoriasis involves the migration and activation of several immune cells, including T helper 17 cells and γδ T cells, and the secretion of proinflammatory cytokines, such as TNF-a, IL-12, IL-17, and IL-23." (PMID 39971882, 2025). "TNF inhibitors have long been used to treat psoriasis with satisfactory PASI75 responses." (PMID 40554357, 2025). "The acylated derivatives of luteolin inhibit imiquimod-induced psoriasis lesions in mice by down-regulating the expressions of TNF-α and IL-6 in the mouse skin tissue, increasing the contents of superoxide dismutase (SOD) and glutathione (GSH), and reducing the content of malondialdehyde (MDA)." (PMID 40144571, 2025). "In psoriasis, curcumin exhibits its anti-inflammatory effects by reducing the expression of cytokines such as interleukin-17A (IL-17A), interleukin-17F (IL-17F), interleukin-22 (IL-22), IL-6, IL-1β, and TNF-α, and by inhibiting NF-κB activation." (PMID 40718452, 2025). "Psoriasis is also triggered when genetic or environmental factors activate plasmacytoid dendritic cells, leading to the production of numerous proinflammatory cytokines, including tumor necrosis factor (TNF)-α, interferon (IFN)-γ, and interleukins." (PMID 40508280, 2025). "TNF-α and IL-6 are the important cytokines involved in inflammation in psoriasis." (PMID 40733073, 2025). "Therapeutic modulation of oxidative stress through diet, food supplements and systemic agents including biologics (such as anti-TNFα and anti-IL- 17 agents) and dimethyl fumarate has been reported, confirming the pivotal role of oxidative stress in psoriasis and psoriatic comorbidities pathogenesis." (PMID 40358870, 2025). "Recent studies have shown that Myr exerts anti-inflammatory properties by modulating key signaling pathways involved in immune responses, including inhibiting the production of pro-inflammatory cytokines such as IL-6, IL-1β, and TNF-α, which are central to psoriasis pathogenesis." (PMID 41471291, 2025). "In psoriasis, therapeutic strategies targeting IL‐23 and IL‐17 have shown superior efficacy over TNF inhibitors, while the former may be less beneficial in inflammatory bowel disease." (PMID 40757098, 2025). "We suggest that IGRA may be more cost-effective for LTBI screening in patients undergoing anti-TNF therapy, especially in those with concomitant immunosuppression or skin conditions such as psoriasis." (PMID 40711067, 2025). "Additionally, psoriasis lesions exhibit a more significant presence of Th17 cells than normal skin, with some Th17 cells producing TNF-α and IFN-γ." (PMID 40141293, 2025). "Interestingly, the psoriasis-related inflammatory factors, including TNF-α, IL-17, IL-22, OSM, and IL-1α, promoted YAP1 up-regulation in keratinocytes, as indicated by increased YAP1 expression (& f)." (PMID 40108109, 2025).
psoriasis (continued). "In psoriasis, interleukin (IL)‐17A is involved in the formation and maintenance of the pathological conditions through potentiation with tumor necrosis factor alpha (TNFα), interferon γ, and other cytokines." (PMID 39611573, 2025). "The connection between TNF-alpha inhibitors and the increased incidence of seborrheic keratoses (SKs) raises important questions about the vast dermatologic effects of these biologic therapies in psoriasis patients." (PMID 40141829, 2025). "In psoriasis, cytokines such as TNF-α, IL-17, and IL-23 are critical drivers of the IL-23/Th17 axis, which promotes keratinocyte hyperproliferation and inflammatory amplification through a feed-forward loop involving antimicrobial peptides, chemokines, and pro-inflammatory mediators." (PMID 40909165, 2025). "As such, TNF-alpha antagonists decrease inflammatory signaling cascades and the production of cytokines that would otherwise result in keratinocyte proliferation, which is abnormally increased in psoriasis." (PMID 40546629, 2025). "Additionally, the drug survival of IL-17 inhibitors used for non-psoriasis-related reasons was significantly poorer than that of TNF inhibitors." (PMID 40615873, 2025). "In an open-label proof-of-concept trial, treatment with RGRN - 305 led to marked clinical improvement in a subset of patients with moderate-to-severe psoriasis, accompanied by molecular and histological normalization of key inflammatory pathways, including TNF-α, IL - 23, and IL - 17A signaling." (PMID 40948777, 2025). "Measures of periodontitis distance between the cemento‐enamel junction and alveolar bone crest (CEJ–ABC) and number of osteoclasts and psoriasis (epidermal thickness and infiltrate cells (per 0.03mm2)) severity, as well as systemic inflammation (IL‐6, IL‐17A and TNF‐α) were collected." (PMID 40277096, 2025). "TNF-α is an important cytokine in the pathogenesis of both psoriasis and TB." (PMID 40310305, 2025). "Assessing these changes could provide insights into how TNF-α inhibition affects vitamin D signaling, thereby deepening our understanding of psoriasis pathophysiology and optimizing future treatment strategies." (PMID 40699711, 2025). "Psoriasis biomarkers include keratins related to keratinocyte differentiation (K1 and K10) and activation (K6 and K16), as well as pro-inflammatory cytokines (IL-6, IL-8, IL-18, and TNF-α)." (PMID 41299626, 2025). "Dendritic cells and macrophages in the dermis of psoriasis produce IL-23, which induces the activation of Th17 cells and γδ T cells and the release of inflammatory cytokines, such as IL-17A, IL-17F, IL-22, IL-6 and tumor necrosis factor-α (TNF-α)." (PMID 40303403, 2025). "Furthermore, in an in vitro psoriasis model where normal keratinocytes were stimulated with the M5 cytokine cocktail (TNF-α, IL-17A, IL-22, IL-1α, and oncostatin M), DGAT2 expression was similarly reduced." (PMID 40694426, 2025). "Consequently, this research provides valuable insights into the binding ability of phytoconstituents of VT oil against IL-17A and TNF-α, paving the way for the development of novel drugs for the treatment of psoriasis." (PMID 40892753, 2025). "TNF-α inhibitors, mainly including Etanercept, Infliximab, Adalimumab, Certolizumab, and Golimumab, are the earliest approved monoclonal antibodies for relieving psoriasis symptoms." (PMID 40299379, 2025). "One illustrative case involved a psoriasis patient who developed NV during therapy with the tumor necrosis factor (TNF) inhibitor etanercept; extensive work-up in that case was negative for infections (including TB) or autoimmune disease, implicating the biologic drug as the trigger." (PMID 41267735, 2025). "The significant adjunctive effect of periodontal therapy to TNF‐α inhibitor for the treatment of psoriasis supports the importance of the early diagnosis and treatment of periodontitis in individuals affected by comorbid psoriasis." (PMID 40277096, 2025).
psoriasis (continued). "In addition to TNF-α inhibitors, biologics approved for moderate-to-severe psoriasis include IL-12/23 inhibitors (Ustekinumab), IL-17 inhibitors (Ixekizumab, Secukinumab, Brodalumab, Bimekizumab), and IL-23 inhibitors (Guselkumab, Risankizumab, Tildrakizumab)." (PMID 40740781, 2025). "TNF-α plays an essential role in the pathogenesis of psoriasis as well as NAFLD." (PMID 38473907, 2024). "As the use of TNF-α inhibitors is associated with an elevated risk of infections, targeting TSLP may be more suitable for treating psoriasis." (PMID 38666958, 2024). "Sericin-coated film reduced IL-1β and TNF-α levels in rat psoriasis model." (PMID 38773312, 2024). "The correlation between IBD and psoriasis clinically is underscored by shared immunopathogenic mechanisms, involving T-cell dysregulation and pro-inflammatory cytokines like IL-17, IL-23, and TNF-α." (PMID 39463646, 2024). "Furthermore, a synergistic impact of IFN-γ and TNF-α on the immunopathogenic mechanism has been observed in the concurrent presence of atherosclerosis and psoriasis." (PMID 39104857, 2024). "NK cells may contribute to the development of fibrosis by releasing IFN- γ, TNF, and IL-22, among other cytokines, in psoriasis and MASLD." (PMID 38917217, 2024). "To further investigate whether Gpr15lg can regulate immune response in psoriasis, we detected the level of IL-1α, TNF-α, IL-1β and S100A7 by qRT-PCR and IHC." (PMID 38393364, 2024). "Notably, treatment with TNF-α inhibitors improved clinical outcomes in psoriasis patients by enhancing PON1 activity, underscoring the link between PON1 activity and inflammation." (PMID 39456475, 2024). "The serum TNFα can be used as a predictor for response to therapy in psoriasis patients." (PMID 38965465, 2024). "Despite the prominent clinicopathological features of psoriasis, including a shortened cell cycle and hyperproliferation of keratinocytes, research has focused predominantly on the role of tumor necrosis factor-α (TNF-α) and the IL-23/IL-17A axis in driving disease pathogenesis." (PMID 38446584, 2024). "In addition, psoriasis and MetS share a common state of chronic low‐grade inflammation, and inflammatory markers such as IL‐6 and TNF‐α are increased in patients with psoriasis and MetS." (PMID 38174774, 2024). "Regulatory factors such as IFN, IFN-γ and TNF promoted the transformation of fibroblasts from fibrotic to inflammatory state in psoriasis lesions, and PANoptosis might play a role in this process." (PMID 39480805, 2024). "The TNFα-IL-23-Th17 axis comprises central signaling pathways pivotal in T-cell-mediated psoriasis." (PMID 39684717, 2024). "Research has demonstrated that PAR2 expression is elevated in the epidermis of psoriasis patients, and it may contribute to the pathogenesis of psoriasis by raising TNF-α." (PMID 39301020, 2024). "Given the fact that glucocorticosteroids are effective in treating psoriasis and that they reduce the expression of TNF-α and IL-1, it is possible that glucocorticoids might affect the IL-1R-to-IL-1 ratio through the regulation of these cytokines." (PMID 38666958, 2024). "Serum TNF‐α levels for the Psoriasis group are higher in magnitude but insignificant (p = 0.381)." (PMID 38363081, 2024). "TNF also activates dermal dendritic cells and macrophages and acts alongside IL-17 to promote the differentiation and proliferation of keratinocytes, driving the formation of psoriasis plaques." (PMID 38258121, 2024). "Overall results revealed that TNF-alpha inhibitors elevated high-density lipoprotein levels in patients with psoriasis (WMD = 2.31; 95% CI: 0.96, 3.67; P = 0.001), which was supported by the results of sensitivity analyses excluding the effect of lipid-lowering drugs." (PMID 38500874, 2024). "In addition to TNF-α, dendritic cells play a pivotal role in regulating immune responses in both psoriasis and IBD." (PMID 39463646, 2024).
psoriasis (continued). "It was reported that macrophages were primed to favor M1 to M2 among psoriasis carriers 85, and treating the patients with TNF-α inhibitors could reduce the disease activity by attenuating the M1 phenotype 86." (PMID 39494336, 2024). "In particular, T cells and their cytokines, such as TNF-α, IL-23, IL-12, and IL-6, are known to play a central role in psoriasis pathogenesis, leading to the activation of cascades of inflammatory responses that promote keratinocyte proliferation and neutrophil recruitment." (PMID 38699235, 2024). "Alcohol drinking may exacerbate the inflammatory process among psoriasis patients through increasing the production of tumor necrosis factor (TNF)-α and enhancing the activity of pro-inflammatory cytokines, which lead to the deterioration of psoriasis." (PMID 39026285, 2024). "However, TNF‐α stimulation promoted the production of psoriasis‐related inflammatory mediators along with the inhibition of Gal‐3 expression in keratinocytes." (PMID 39230472, 2024). "There have been studies showing the occurrence of anti-TNF-α-induced lupus-like syndrome, systemic lupus erythematosus, interstitial lung disease, new-onset or worsening of psoriasis, and cutaneous and systemic vasculitis at average intervals of 16.2-34.5 months following the onset of treatment." (PMID 39463588, 2024). "Therefore, TNF L-SNA was suggested as a potential therapeutic tool (topically applied SNA-mediated antisense therapy) for psoriasis." (PMID 38951806, 2024). "TNF inhibitors (including adalimumab, infliximab, etanercept) are used for several inflammatory conditions associated with CNO/CRMO including IBD, inflammatory arthritis, and psoriasis." (PMID 39209330, 2024). "The immune patterns characterizing psoriasis lesions of patients were compared with those detectable in classical, stable plaque-type psoriasis or paradoxical psoriasis induced by anti-TNF-α therapy, mostly sustained by adaptive and innate immunity processes, respectively." (PMID 38495872, 2024). "CYFRA21-1, the soluble fragment of CK-19 found in the bloodstream, could indicate increased tissue apoptosis, possibly due to increased TNF-α-mediated apoptosis in patients with psoriasis." (PMID 38813379, 2024). "Anti-TNF-α was one of the first biologic therapies used in psoriasis." (PMID 39767248, 2024). "Tumor necrosis factor represents another, more upstream, therapeutic target for psoriasis." (PMID 38992724, 2024). "TNF-α is the founder cytokine that initiates downstream inflammatory signaling in psoriasis." (PMID 38642273, 2024). "The correlation between psoriasis and atherosclerosis has been conceptualized as “one syndrome and two plaques” based on the analogous inflammatory cytokine profiles shared by both conditions, such as TNF-α and IL-17A." (PMID 39104857, 2024). "Therefore, 10.3% of the pregnant patients treated with an anti-TNF drug had a diagnosis of psoriasis." (PMID 39065754, 2024). "Interestingly, the level of LOR in psoriasis patients can be upregulated after using TNF-α antagonists." (PMID 38606161, 2024). "Interestingly, incubation of 3D full-thickness skin models with recombinant human IL-17A, IL-22 and TNF-alpha for 5 days leads to hyperkeratosis and parakeratosis, both characteristic of psoriasis." (PMID 37707681, 2024). "Given that TNFα expression is significantly upregulated in OSA patients, we hypothesize that OSA may initiate pyroptosis in epidermal keratinocytes through changes in TNFα levels, contributing to the pathology of psoriasis." (PMID 39595526, 2024). "Notably, the release of inflammatory factors, such as tumor necrosis factor (TNF-α), interferon (IFN)-γ, interleukin (IL)-17, IL-22, IL-23, and IL-1β, is the primary cause of psoriasis." (PMID 39684717, 2024).
psoriasis (continued). "In the present study, LCAA-PSF was found to effectively slow down the inflammatory cytokine secretion of IMQ-induced psoriasis, including the expression of IL-23, IL-17A, TNF-α, and IL-6 in the serum and the expression of IL-17, Ki67, CK5/6 and VEGF in the affected skin area." (PMID 39062965, 2024). "IL-17 and TNF-α play a synergistic role in the pathogenesis of diseases such as psoriasis." (PMID 38708351, 2024). "In addition, psoriasis related proinflammatory mediators such as TNF‐α, IL‐1β, IL‐17A, and IFN‐γ can induce endoplasmic reticulum stress in a variety of immune cells." (PMID 38174774, 2024). "On the other hand, patients responding to methotrexate may present with milder cases of psoriasis and, consequently, have lower levels of TNF and IL-17." (PMID 37634972, 2024). "When we analyzed the differences in the cell response to cytokine stimulation (IL17, IFNγ, TNFα—a cocktail mimicking the cytokine background in psoriasis), we observed that the average level of gene expression alterations appeared to be less prominent in the knockdown cells." (PMID 38674130, 2024). "In the maintenance phase of psoriasis, the TNF-α/IL-23/IL-17 axis assumes a crucial role." (PMID 38504983, 2024). "Psoriasis is characterized by a high serum level of TNF-α, linking PsO and MetS." (PMID 39204094, 2024). "In the last 10–15 years, the introduction of biological therapies, such as TNF-α, IL-12/23, and IL-17 inhibitors in psoriasis and IL-6, CD20, TNF-α, and CD80/86 inhibitors in RA, is expected to influence the rate of atherothrombotic complications in patients with psoriasis and RA." (PMID 38927529, 2024). "Importantly, it was reported that Rho alleviated skin inflammation in a mouse model of psoriasis by inhibiting the expression of TNF-α." (PMID 38710713, 2024). "However, the difference was not statistically significant (P > 0.05), leading the authors to conclude that both TNF-α and IL-17 inhibitors similarly moderate the progression of atherosclerosis in psoriasis patients." (PMID 39739136, 2024). "It should be noted that treatment of psoriasis may involve biologics that affect blood cytokine levels (i.e., IL-12, IL-23, and TNF-α), with an overall reduction in inflammation." (PMID 39335361, 2024). "Loss of efficacy over time (secondary failure), the need for higher doses for spine involvement, or paradoxical reactions associated with IL-17 inhibition similar to lupus-like syndrome or psoriasis after TNF inhibition arise as possible explanations for these unexpected events." (PMID 39125513, 2024). "Keratinocytes and pDCs respond to DAMPs and PAMPs by binding their TLRs and subsequently producing proinflammatory cytokines such as IFN-β and TNF-α.The initial release of proinflammatory cytokines promotes the primary T-cell-mediated response of inflammation in psoriasis." (PMID 39337637, 2024). "Moreover, both the number and activity of lysosomal components, including histone proteases D and L, were significantly reduced in KCs stimulated with TNF-α, which indicated impaired autophagy in AD and psoriasis." (PMID 38606161, 2024). "Integrating current research, OSA may promote pyroptosis in epidermal keratinocytes through TNFα overexpression and increased ROS production, which could be a key factor in the higher incidence of psoriasis among OSA patients." (PMID 39595526, 2024). "In addition, the 3D TNFF‐α, IL17A and IL22 skin models clearly demonstrated the roles of TNF‐α, IL‐17A and IL‐22 in the formation of the epidermal structure and expression of psoriasis‐related molecules." (PMID 39624730, 2024). "To investigate whether TSG plays a role in psoriasis treatment, we stimulated HaCaT cells with 50 ng/mL TNF-α and 5 μM TSG for 24 h." (PMID 38429819, 2024).